ITK (IL2 inducible T cell kinase)
Diseases named in the same sentence as ITK in open-access papers (continued):
Sharing a sentence is not in itself a finding about the gene and the disease.
tumor (50 papers, 2015 to 2026). "ITK-deficient CD19-CAR-T cells showed better control of tumor relapse, leading to more sustainable therapeutic effects." (PMID 39589809, 2024). "It was recently reported that ITK gene expression is higher in tumor tissues than in normal tissues and associated with poor prognosis in head and neck cancer." (PMID 34283052, 2021). "ITK-deficient CAR-T cells significantly improve control of tumor relapse in vivo." (PMID 39589809, 2024). "Therefore, in contrast to Th1 cells, that are associated with effective anti-tumor immunity, Th2 cells, due to a relative abundance of ITK compared with RLK (i.e. a high ITK/RLK ratio), are particularly sensitive to ibrutinib, which does not inhibit RLK." (PMID 28031823, 2016). "In this tumor model, both ITK-KO and nt-KO CD19-CAR-T cells efficiently cleared tumor cells 14 days after infusion." (PMID 39589809, 2024). "In fact, following exposure to tumor cells, there was a significantly decreased fraction of terminally differentiated cells and an increased fraction of central memory cells in ITK-KO CD19-CAR-T cells compared with nt-KO CD19-CAR-T cells." (PMID 39589809, 2024). "ITK deficiency decreases exhaustion and increases memory in CD19-CAR-T cells, resulting in improvement of CAR-T cell expansion and better control of tumor relapse." (PMID 39589809, 2024). "Our study reveals that ITK-deficient CAR-T cells exhibit enhanced expansion and long-term survival in response to tumor antigen stimulation." (PMID 39589809, 2024). "Similar to the AE17 tumor model, combined ITK inhibitor and anti-PD-1 treatment decreased tumor growth and improved the survival of mice." (PMID 37735204, 2023). "In this study, we report that ITK inhibition increases TCF1 + CD8 + T cell numbers in the tumor draining lymph nodes in vivo." (PMID 37735204, 2023). "Since ITK is in the downstream of TCR signaling pathway involving in T cell activation, ITK inhibitor was administrated a few days after tumors were established to prevent undesired blocking of priming of tumor-specific T cells." (PMID 37735204, 2023). "On day 35, there were 5 mice whose tumor were still controlled in the anti-PD-1 combined with ITK inhibitor treatment group." (PMID 37735204, 2023). "Overall, these results from ICB insensitive tumor models demonstrate that ICB and ITK inhibitor treatment synergize and potently suppress tumor growth." (PMID 37735204, 2023). "Taken together, our studies demonstrated that ASK120067 exerted preclinical anti-tumor activities against B-/T-cell malignancy by targeting BTK/ITK." (PMID 36588692, 2022). "They demonstrated that ITK-SYKCD4-creERT2 mice with homozygous/heterozygous PDCD1 deficiency were affected by the severe invasion of ITK-SYK+PD-1−CD4+ T-cells into the solid organs, indicating that PD-1 is a haploinsufficient tumor suppressor." (PMID 35625999, 2022). "All the data suggested that ITK was a tumor suppressor gene, especially a gene that inhibited cancer metastasis both in mouse models and patients." (PMID 34702300, 2021). "We understand that it is better to reveal the potential ITK transcriptional mechanism by detecting the RNA and protein expression in corresponding cancer cells and tumor tissues." (PMID 34702300, 2021). "Then we discovered that ITK was with significantly lower expression (p = 0.036) in tumor (n = 9) than that in normal (n = 7) samples." (PMID 34702300, 2021). "We found that low expression levels of ITK, and DOK2 in LUAD were associated with poor prognosis, possibly affecting tumor progression via the transmembrane receptor PTK signaling pathway." (PMID 32775050, 2020). "The G2/M transition-related cell cycle proteins cyclinB1 and phosphorylated cdc2 were decreased in ITK inhibitor-treated tumor cells." (PMID 30814910, 2019). "Through the off-target inhibition of ITK (interleukin-2-inducible T-cell kinase), ibrutinib is able to polarize T-cell response towards à Th1 tumor rejection-prone phenotype." (PMID 31205470, 2019).
tumor (continued). "The ITK inhibitor reduced tumor growth by 11.49%, 24.53% and 53.82% (P = 0.502, P = 0.033 and P = 0.000) in response to 10, 25 and 40 mg/kg BMS-509744 treatment, respectively." (PMID 30814910, 2019). "Immunohistochemical staining analysis demonstrated that more than half of the patients exhibited phosphorylated ZAP70, ITK and PLCγ1 in tumor tissues of AITL patients, suggesting the continuous activation of the TCR signaling in AITL." (PMID 30814910, 2019). "As we observed significantly improved expansion and long-term persistence of ITK-deficient CD19-CAR-T cells compared with nt-KO CD19-CAR-T cells in vivo, we speculated that mice receiving ITK-KO CD19-CAR-T cells might be better protected against tumor relapse." (PMID 39589809, 2024). "Therefore, we used this model to assess the function of ITK in CD19-CAR-T cell activity against tumor relapse." (PMID 39589809, 2024). "Interestingly, upon tumor clearance, the abundance of ITK-KO CD19-CAR-T cells peaked at a significantly higher level than that of nt-KO CD19-CAR-T cells, in agreement with the enhanced expansion of ITK-KO CD19-CAR-T cells." (PMID 39589809, 2024). "Interestingly, even after tumor relapse at day 56, animals that received ITK-KO CD19-CAR-T cells exhibited better control of the relapsed tumor, leading to significantly improved survival." (PMID 39589809, 2024). "Our studies indicate that intermittent inhibition of ITK could be a strategy to reinvigorate exhausted CTLs and improve anti-tumor immunotherapies in resistant cancers." (PMID 37735204, 2023). "Since both concentration and treatment schedule have not been optimized in our in vivo anti-tumor studies, further studies are needed to determine whether the anti-tumor benefit of ITK inhibition in ICB can be improved." (PMID 37735204, 2023). "However, only in the presence of anti-PD-1, the beneficial effects of ITK inhibitor treatment can be conferred to tumor control and this is accompanied by increased tumor-infiltrating CD8 + T cells in tumors." (PMID 37735204, 2023). "We found that only ITK inhibitor combined with anti-PD-1 treatment suppressed tumor growth." (PMID 37735204, 2023). "Therefore, ibrutinib-mediated inhibition of ITK can robustly enhance anti-tumor immune responses by favoring TH1 differentiation and promoting the effector functions of CD8 cytotoxic T cells." (PMID 34778053, 2021). "To further verify the prognostic capacity of ITK, we collected primary tumor samples from patients with HCC who underwent liver resection in our medical center between 2015.01.01 and 2017.12.31 (n = 176) and carried out IHC staining to determine ITK expression in the tissues." (PMID 34282055, 2021). "In colon cell lines and rodent models, monotherapy using the ITK inhibitor, Ibrutinib, was reported to perform poorly in tumor suppression, whereas the combination of Ibrutinib and a programmed cell death 1 ligand 1 (PD-L1) inhibitor showed significant antitumor capacity." (PMID 34282055, 2021). "To identify the immune-related role of ITK in the tumor microenvironment (TME), we applied MCP-counter and CIBERSORT methods to estimate absolute abundance scores of 8 major immune cell types, endothelial cells and fibroblasts and the relative cellular fraction of 22 immune cell types." (PMID 34702300, 2021). "Ki67 staining was stronger in ITK-expressing SAS tumor cells than in mock control cells." (PMID 34283052, 2021). "As ITK disruption can contribute to the pathogenesis of certain infectious, autoimmune, and neoplastic diseases, this “side” activity has represented an interesting point of speculation." (PMID 34065833, 2021). "ITK-expressing SAS tumor cells grew faster than mock control cells." (PMID 34283052, 2021). "Meanwhile, we discovered patients with these serious DNA mutation were almost low-ITK expression, un-regional metastasis and dead with tumor, which could partially explain the low levels of ITK expression in tumor tissues and indicate its prognostic role." (PMID 34702300, 2021).
tumor (continued). "Further validation of GSEA and tumor-infiltrating immune cell proportion analysis supported that the levels of ITK affected the immune activity of TME and could be a prognostic biomarker for patients with BC." (PMID 34867821, 2021). "Here, this inhibitor was able to block ITK which led to an anti-tumour activity." (PMID 32808093, 2020). "The BTK/ITK inhibitor ibrutinib reprogrammes the tumour-induced immunosuppressive population of myeloid lineage (MDSCs) into mature DCs by blocking BTK, increases the proportion of mature DCs in the tumour and lymphoid organs, and promotes antitumour T cell activity." (PMID 32025027, 2020). "In conclusion, over the last 30 years, a great deal of progress has been made from discovering this enzyme to unravelling its structure and molecular function as well as its detrimental role in autoimmune and tumour pathogenesis, placing ITK in the focus as a key target for drug design." (PMID 32808093, 2020). "Subsequently, this blockage of ITK led to a reduced tumour growth in Hut78-xenografted nude mice." (PMID 32808093, 2020). "Besides that, there are also several well-known cases where an aberrant activation of ITK in already persisting tumours was found." (PMID 32808093, 2020). "ITK inhibition was reported to enhance T-cell anti-tumor immunity." (PMID 32947901, 2020). "Targeting Bruton’s tyrosine kinase (BTK) expressed in MDSCs in tumor-bearing mice by Ibrutinib, an irreversible inhibitor of BTK and IL2-inducible T-cell kinase which widely used for the treatment of B-cell malignancies in clinical, reduces the frequency of MDSCs in both the spleen and tumor." (PMID 32508809, 2020). "It remains unclear to what extent these T-cell changes are related to the inhibition of ITK or the reduction in tumor bulk and immunosuppressive mechanisms active in untreated CLL." (PMID 31861854, 2019). "Moreover, ibrutinib also binds to and inhibits interleukin-2-inducible T-cell kinase (ITK), thereby leading to a T-helper (Th) cell 1 polarization in vitro and in vivo, which aids in inducing an anti-tumor immune response." (PMID 28100240, 2017). "Interestingly, we noted a significant downregulation of the expression of multiple coinhibitory molecules associated with CAR-T cell exhaustion, including LAG-3, PD-1, and TIM-3, in ITK-KO CD19-CAR-T cells compared with nt-KO CD19-CAR-T cells 48 hours after coculture with tumor cells." (PMID 39589809, 2024). "Furthermore, ITK-KO CLL-CAR-T cells showed better control of tumor relapse." (PMID 39589809, 2024). "When CD8 + T cells in draining lymph nodes were assessed at the time that animals reached the predefined endpoint, more donor OT-I cells could be found in the tumor draining lymph node (dLN) of animals treated with ITK inhibitor and nearly all of these cells maintained TCF1 expression." (PMID 37735204, 2023). "Moreover, alterations correlated with distant metastasis emereged with significantly increased expression in SAMRCD1 in low-ITK group, but CD244 and SOCS1 in high-ITK group (p < 0.001), which indicated as oncogene or tumor suppressors in numerous cancers and potential therapeutic targets." (PMID 34702300, 2021). "ITK may be a potential indicator for prognosis prediction in patients with BC, and its biological behavior may promote our understanding of the molecular mechanism of tumor progression and targeted therapy." (PMID 34867821, 2021). "Furthermore, the BTK/ITK inhibitor ibrutinib efficiently limits the IL-4-producing Th2 cell population and inhibits cytokine production and direct signaling to induce the activation of tumor cells." (PMID 30814910, 2019). "Methylation analyses from TCGA and GEO datasets indicated hypermethylation of ITK and hypomethylation of ZNF683 in tumour samples, suggesting epigenetic regulation of these immune-related genes." (PMID 41301032, 2025).
tumor (continued). "Methylation profiling revealed hypermethylation of ITK and hypomethylation of ZNF683 in tumour tissues, suggesting an epigenetic basis for altered gene expression." (PMID 41301032, 2025). "To further determine the role of ITK in CD19-CAR-T cells, we examined cell expansion, proliferation, and apoptosis in ITK-KO CD19-CAR-T cells and nt-KO CD19-CAR-T cells after coculture with tumor cells." (PMID 39589809, 2024). "To assess the long-term in vivo effects of ITK deletion on CLL-CAR-T cells, we employed a CLL mouse model using NPG mice injected intravenously with MEC1 tumor cells, followed by infusion with ITK-KO or nt-KO CLL-CAR-T cells." (PMID 39589809, 2024). "To test the long-term effects of ITK deletion on CD19-CAR-T cells in vivo, we first used a CLL mouse model of NOD-PrkdcscidIl2rγnull (NPG) mice bearing MEC1 tumor cells (injected intraperitoneally) followed by infusion with ITK-KO or nt-KO CD19-CAR-T cells." (PMID 39589809, 2024). "Taken together, these data illustrated that ITK inhibitor improves the antitumor effects of ICB, by increasing pre-terminally exhausted TCF1 + tumor-specific cells, cells known to be required for the protective effect of ICB, in the draining lymph nodes." (PMID 37735204, 2023). "On the other hand, ibrutinib’s off-target inhibition of JAK3, ITK, and EGFR means that it can target oncogenic pathways other than BTK in tumor cells and act as a T-cell modulator in combination immunotherapy." (PMID 36903645, 2023). "PPI network analysis revealed these genes and modules were mainly related to tumor progression (LOXL1, IKBKE, LNX1, FOXA2, FGF17, and FGF2) and immune response (STAT4, IL23R, LTA, ITK, and IL19)." (PMID 36611170, 2023). "We found that there were more tumor infiltrating CD8 + T cells in the tumors which were suppressed efficiently by anti-PD-1 and ITK inhibitor combined therapy, when compared to the cells in tumors from all the other treatments." (PMID 37735204, 2023). "The remaining six genes (e.g., PPP3CC, ITGA5, ITK, CDC25B, CCND2, and THY1) were expressed at higher levels in CD45+ TAS as compared to CD45+ tumor." (PMID 36230846, 2022). "Meanwhile, ITK expression also presented statistical significance in age, TNM staging, tumor size classification, metastasis classification, and histology." (PMID 34867821, 2021). "In lymphocytes, the TEC family tyrosine-kinase proteins BTK (bruton tyrosine kinase), ITK (IL2 inducible T-cell kinase), and TEC are PI3K effectors that are activated by PIP3, with potential anti-tumor therapeutic implications." (PMID 32033478, 2020). "To further evaluate the apoptosis status of tumor after the treatment of BMS-509744, we performed TUNEL staining on paraffin sections of tumor samples collected from H9 xenografts post ITK inhibitor treatment." (PMID 30814910, 2019). "Ibrutinib (NCT03646461), a Bruton's tyrosine kinase inhibitor, inhibits IL-2 inducible T-cell kinase (ITK), to strengthen specific anti-tumor responses." (PMID 31681613, 2019). "Given that ibrutinib shows off-target inhibition of JAK3, ITK and EGFR, it can be used to target oncogenic pathways other than BTK in tumor cells and as a T-cell modulator in combination immunotherapy." (PMID 29455639, 2018). "Additionally, ITK inhibitor-treated CAR-T cells also exhibited increased cytotoxicity against malignant B cells and prolonged survival in tumor-bearing mice." (PMID 41792111, 2026). "Deletion of ITK during CAR-T cell production leads to enhanced CAR-T cell expansion and memory development, along with reduced cell apoptosis and exhaustion upon repeated exposures to tumor cells." (PMID 39589809, 2024). "Ibrutinib targets the B-cell receptor pathway and immune cells in the tumor microenvironment via BTK, as well as kinases relevant to solid tumor treatment, including tyrosine kinase ETK/BMX and interleukin-2–inducible T-cell kinase (ITK)." (PMID 37296940, 2023).
tumor (continued). "Besides BTK inhibition, it also affects other TEC family kinases, such as interleukin-2-inducible T-cell kinase (ITK), and therefore modifies cell adhesion within the tumor microenvironment as well as modulates chemotaxis and cell-to-cell signaling." (PMID 36903645, 2023). "XCL1 forms a connection with tumor suppressors: IRF8 and ITK in early cancer stages." (PMID 35610556, 2022). "Mechanistically, ITK is required for TCR signaling and CXCR4 signaling, and thus critical for malignant T cell proliferation, differentiation and migration, while preventing anti-tumor immune responses by inhibiting TH1 CD4 T cell differentiation." (PMID 34778053, 2021). "The results illustrated that high expression of BC patients had a more prolonged overall survival (OS) time than ITK low expression BC patients (p = 0.009), and ITK expression also presented the statistical significance in age, TNM staging, tumor size classification, and metastasis classification." (PMID 34867821, 2021). "In addition to its direct anti-tumor effect on BTK, ibrutinib irreversibly binds ITK (Interleukin-2 inducible kinase) and inhibits downstream activation of Th2 cells after TCR stimulation both in vitro and in vivo." (PMID 34065833, 2021). "To further investigate the role of ITK in regulating T cell activation, exhaustion, and memory, we determined the protein expression of multiple key molecules involved in these processes between nt-KO and ITK-KO CD19-CAR-T cells under steady state or cocultured with tumor cells." (PMID 39589809, 2024). "The body weight of tumor-bearing mice was not significantly affected post ITK inhibitor treatment." (PMID 30814910, 2019). "Paradoxically, inhibiting ITK in T cells may be efficacious in cancer, as this may enhance Th1-skewing of CD4+ T-cells and thereby improved memory formation and functionality of CD8+ T-cells, potentially leading to improved anti-tumor immunity." (PMID 29455639, 2018). "Our results suggest that deletion of ITK during CAR-T cell production may be a useful strategy for the development of sustainable and functional CAR-T cell therapy, which will potentially benefit patients whose T cell functional quality is low, as well as those who suffer from tumor relapses." (PMID 39589809, 2024). "ITK inhibition did not change the expression of TCF1 and TOX in tumor specific CD8 + T cells in tumors, while anti-PD-1 treatment decreased TCF1 expression." (PMID 37735204, 2023). "Chemotaxis is also involved in the “Role of tumor-infiltrating B cells in anti-tumor immunity” pathway map and includes BTK and JAK3, but does not include ITK." (PMID 34803999, 2021). "Our data show that ITK treatment alone has no therapeutic effects in solid tumors in vivo, while it directly reinvigorates in vitro exhausted CTLs and increases tumor-specific CD8 + T cells in the tumor draining lymph node." (PMID 37735204, 2023). "We showed that while pharmacological ITK inhibition could mitigate T cell exhaustion and promote memory phenotype in CAR-T cells derived from patients with CLL, it only showed a trend but no significant increase of CLL-CD19-CAR-T cells in the tumor-bearing mouse model in vivo." (PMID 39589809, 2024).